CLDN12 (claudin 12)
Description:
Plays a major role in tight junction-specific obliteration of the intercellular space, through calcium-independent cell-adhesion activity.
Tractability: Antibody: UniProt places it where antibodies can reach, with high confidence; its Gene Ontology location is reachable by antibodies, with high confidence; UniProt predicts a signal peptide or a membrane-spanning region. PROTAC: ubiquitination databases record sites on it.
Gene: Protein-coding gene on chromosome 7 (90,383,721 to 90,513,402, forward strand). Ensembl gene ENSG00000157224.
Subcellular location: Cell junction, tight junction; Cell membrane
Pathways (Reactome):
Cell-Cell communication: Tight junction interactions
Gene Ontology:
Molecular function: protein binding; identical protein binding
Biological process: calcium-independent cell-cell adhesion; maintenance of blood-brain barrier; tight junction assembly
Cellular component: plasma membrane; bicellular tight junction; cell periphery; lateral plasma membrane; tight junction
Genetic constraint (gnomAD): Loss-of-function variants: 9 observed, 16.34 expected, observed/expected ratio (o/e) 0.55, 90% interval 0.33 to 0.96. The upper end of that interval is the gene's LOEUF score, 0.96, which puts it in group 4 of 6, group 1 being the genes least tolerant of losing a copy. Missense variants: 233 observed, 314.81 expected, observed/expected ratio (o/e) 0.74, 90% interval 0.66 to 0.82. Synonymous variants: 140 observed, 129.02 expected, observed/expected ratio (o/e) 1.09, 90% interval 0.94 to 1.25.
Homologues: Orthologues: chimpanzee CLDN12 (100% identical), macaque CLDN12 (100% identical), dog CLDN12 (97% identical), guinea pig CLDN12 (97% identical), rat Cldn12 (93% identical), mouse Cldn12 (91% identical), tropical clawed frog cldn12 (67% identical), rabbit CLDN12 (61% identical), zebrafish cldn12 (55% identical).